GNMT (glycine N-methyltransferase)
Diseases named in the same sentence as GNMT in open-access papers (continued):
Sharing a sentence is not in itself a finding about the gene and the disease.
prostate carcinoma (21 papers, 2011 to 2025). A carcinoma that arises from epithelial cells of the prostate gland. "Whereas genetic alterations in GNMT have been associated to prostate cancer risk, its causal contribution to the development of this disease is limited to cell line-based studies and correlative human analyses." (PMID 35197445, 2022). "We hereby explored the association of GNMT polymorphisms with prostate cancer risk in individuals of European descent from the Health Professionals Follow-up Study (HPFS)." (PMID 24800880, 2014). "Compared to the study conducted in Taiwanese men, the susceptibility GNMT alleles for prostate cancer had a reverse relationship." (PMID 24800880, 2014). "The strength of this study was that we were able to see the variable associations of GNMT with prostate cancer in different ethnicities." (PMID 24800880, 2014). "A previous study reported a potential association between high GNMT cytoplasmic expression in prostate cancer and lower DFS rate, consistent with our findings." (PMID 24884785, 2014). "For example, particular haplotypes of GNMT (encoding glycine N-methyltransferase) differently predispose individuals to prostate cancer." (PMID 25473435, 2014). "It is therefore uncertain whether these GNMT genetic polymorphisms are associated with prostate cancer risk in other ethnicities such as African Americans." (PMID 24800880, 2014). "Immunohistochemical studies may be performed to further elucidate the association of GNMT with prostate cancer in these men of European descent." (PMID 24800880, 2014). "In Taiwanese men, GNMT was found to be a tumor susceptibility gene for prostate cancer." (PMID 24800880, 2014). "Frequency of GNMT polymorphisms and association with prostate cancer risk." (PMID 24800880, 2014). "Interestingly, a recent study has implied that the cytoplasmic localization of GNMT is associated with lower survival of prostate cancer patients." (PMID 23936142, 2013). "However, the association of GNMT with prostate cancer in other races or ethnicities remains unclear." (PMID 24800880, 2014). "Here we integrate human studies, genetic mouse modeling, and cellular systems to characterize the regulation and function of GNMT in prostate cancer." (PMID 35197445, 2022). "In this line, we confirmed the transcriptional control of GNMT by FOXO1 using shRNA against the transcription factor in prostate cancer cells." (PMID 35197445, 2022). "Altogether, our results provide further support of the heavy oncogenic signal-dependent regulation of GNMT in prostate cancer." (PMID 35197445, 2022). "A previous study has suggested that dysfunctional glycine-N-methyltransferase activity and transfer of a methyl group from S-adenosylmethionine are responsible for accumulation of sarcosine in the prostate cancer tissues and patient’s blood." (PMID 35208208, 2022). "AR activity (by means of the expression of its target KLK3) was consistently correlated with the expression of GNMT in the majority of prostate cancer datasets analyzed." (PMID 35197445, 2022). "On the other hand, siRNA-mediated GNMT knockdown results in an inhibition of proliferation, and induces G1 arrest and apoptosis in prostate cancer cell lines." (PMID 34065390, 2021). "SAM is used in prostate cancer cells for glycine methylation into sarcosine via GNMT; high levels of sarcosine were found to be a biomarker of prostate cancer progression." (PMID 31653965, 2019). "The physiological role of GNMT can also provide insight into its connection with prostate cancer (PC) at various levels, including gene structure, gene expression, and metabolism." (PMID 30061177, 2018). "In studies conducted in Taiwanese men, GNMT was found to be a tumor susceptibility gene for HCC and prostate cancer." (PMID 24800880, 2014). "In men of European descent, the GNMT rs10948059 and STRP1 were associated with prostate cancer risk." (PMID 24800880, 2014).
prostate carcinoma (continued). "In our study of men of European descent, GNMT STRP1 and rs10948059 were indeed associated with prostate cancer risk." (PMID 24800880, 2014). "GNMT is the enzyme responsible for converting glycine to sarcosine, and they showed that knockdown of GNMT attenuated prostate cancer invasion." (PMID 24800880, 2014). "In this study, we tried to determine the association of the GNMT polymorphisms STRP1, INS/DEL and rs10948059 and prostate cancer risk in Americans of European ancestry." (PMID 24800880, 2014). "In light of the important role of this protein in prostate cancer progression, we aimed to characterise further the mechanism of GNMT androgen regulation." (PMID 23997240, 2013). "We first examined the mRNA expression of GNMT in the LNCaP, AR-positive prostate cancer cell line, which is dependent on androgens for growth." (PMID 23997240, 2013). "Non-proteinogenic amino acid sarcosine has a promising potential as a non-invasive marker of carcinoma of prostate as well as GNMT, which is closely connected with the presence and involvement of sarcosine in tissue of prostate tumours." (PMID 23880848, 2013). "Modulating the function of GNMT can be used to develop new strategies for treatment of prostate cancer." (PMID 23880848, 2013). "Treatment of prostate cancer cell lines with androgens resulted in an increase in GNMT expression and a simultaneous decrease in SARDH levels." (PMID 23405127, 2013). "By its function in generating sarcosine, GNMT was predicted to play a critical role in modulating prostate cancer invasion." (PMID 23997240, 2013). "Glycine N-methyltransferase (GNMT) is a S-adenosylmethionine-dependent methyltransferase that has been recently identified as a novel androgen-regulated gene in prostate cancer cells." (PMID 23997240, 2013). "Importantly, GNMT mRNA levels were significantly lower in prostate tumors with PTEN deletion in two independent prostate cancer datasets, thus supporting the results of our mouse model." (PMID 35197445, 2022). "Importantly, we demonstrate that expression of GNMT is required for the onset of invasive prostate cancer in a genetic mouse model." (PMID 35197445, 2022). "However, contrary to its role in HCC, GNMT has been shown to play a role in promoting prostate cancer cell growth and contributes to the progression of prostate cancer." (PMID 33802396, 2021). "Elevated expression of Glycine N-methyltransferase (GNMT) evident from transcriptomics analysis was assumed to be responsible for the induction of SAH and was proposed as a tumor-susceptibility gene in prostate cancer." (PMID 30402498, 2018). "Our earlier studies revealed that the metabolite sarcosine and its biosynthetic enzyme, glycine N-methyltransferase (GNMT) were elevated in prostate cancer, while sarcosine dehydrogenase (SARDH) and pipecolic acid oxidase (PIPOX) that metabolize sarcosine, were reduced in prostate tumors." (PMID 26140362, 2015). "The GNMT short tandem repeat polymorphism 1 (STRP1), 4-bp insertion/deletion polymorphisms (INS/DEL) and the single nucleotide polymorphism rs10948059 were genotyped to test for their association with prostate cancer risk." (PMID 24800880, 2014). "Gnmt−/− mice developed HCC but not prostate cancer, suggesting that other risk factors contributed to the tumorigenesis of prostate cancer besides deficiency or perturbation of the expression level of GNMT." (PMID 24800880, 2014). "GNMT is a susceptibility gene for both HCC and prostatic cancer." (PMID 23883094, 2013). "In addition, analysis of the RefExA microarrays database indicated very low levels of GNMT mRNA in numerous cancer cell lines, including prostate cancer cells, a phenomenon that further questions the proliferation-promoting role of GNMT." (PMID 23936142, 2013). "In addition, experiments carried out in prostate cancer cell lines revealed that androgen treatment up-regulates GNMT expression and that the AR directly binds to the GNMT promoter." (PMID 23997240, 2013).
prostate carcinoma (continued). "Interestingly, GNMT, is reported to be down-regulated in neoplastic tissues in general including human prostate cancer." (PMID 21853037, 2011). "Therefore, increased GNMT and glycine levels may represent novel markers of malignant progression and poor prognosis in prostate cancer." (PMID 38012666, 2023). "In order to address whether the effect of Gnmt deletion was based on prostate cancer cell-autonomous effects, we silenced GNMT in three independent PCa cell lines with differing AR status and GNMT levels (PC3, DU145, and LNCaP) using two different short hairpin RNAs." (PMID 35197445, 2022). "Hence GNMT may play an important role in promoting prostate cancer cell growth via the regulation of apoptosis, and serve as a marker of malignant progression and poor prognosis of prostate cancer." (PMID 34065390, 2021). "However, the association of GNMT with prostate cancer risk in other ethnicities has not been studied." (PMID 24800880, 2014). "In recent years, increasing attention has been paid to the role of GNMT in prostate cancer since the discovery that sarcosine, the metabolite generated by GNMT, was highly elevated during prostate cancer progression to metastasis and, importantly, that it could be detected noninvasively in urine." (PMID 23997240, 2013). "In addition, GNMT could serve as a new tumour marker to diagnose malignant progression of prostate cancer." (PMID 23880848, 2013). "The results imply that variants associated with prostate cancer can be identified through expressional change in the PEX6 gene, but not in the overlapped glycine N-methyltransferase gene which had been considered as a candidate gene." (PMID 28033303, 2016). "GNMT expression tended to be higher in non-cancerous than in prostate cancer and tumor-adjacent tissues; and in the cancer tissues, staining was higher in low stage than high stage cancers." (PMID 24800880, 2014). "Although GNMT acts as a tumor suppressor and was found to be down-regulated in HCC, its role in the pathogenesis of prostate cancer remains unknown." (PMID 24800880, 2014). "We next evaluated whether the regulation of GNMT by PI3K could be translated to non-stratified prostate cancer specimens." (PMID 35197445, 2022). "It is therefore possible that GNMT may be a biomarker for early non-aggressive prostate cancer." (PMID 24800880, 2014).
steatosis (14 papers, 2014 to 2025). Increased lipid within the cytoplasm of cells. "GNMT-deficient mice developed spontaneous steatosis and progressed to NASH by spontaneously activating NK cells in the liver." (PMID 32765518, 2020). "Glycine-N-methyltransferase is involved in glycine metabolism and also plays a significant role in liver fibrosis, steatosis, and neural differentiation." (PMID 40870663, 2025). "In contrast, in cases of glycine N-methyltransferase deficiency, the accumulation of SAM leads to a manifestation of an MASH-like phenotype, progressing from steatosis to fibrosis." (PMID 41274506, 2025). "Individuals with GNMT deficiency or mutated GNMT showed elevated serum levels of aminotransferases, methionine and SAM, and developed steatosis and fibrosis." (PMID 36144184, 2022). "GNMT KO animals spontaneously develop steatosis around three months of age and inflammation and fibrosis of the liver at eight months." (PMID 35216100, 2022). "Morphologically GNMT‐/‐ mouse livers had a higher proportion of microvesicular steatosis and fewer large lipid droplet when compared to WT controls in both diet treatments." (PMID 32951289, 2020). "Steatosis, fibrosis, and HCC develop spontaneously in mice deficient for glycine N-methyltransferase (Gnmt), which encodes an enzyme that catalyzes the transfer of a methyl group to glycine as a way to regulate cellular SAM levels and prevent aberrant methylation of other substrates." (PMID 24802098, 2014). "The heatmap shows the relative expression levels of the four genes (AKR1B10, FABP4, GNMT, and THBS1) in normal, steatosis, and steatohepatitis tissues across the three training datasets." (PMID 39781352, 2025). "Therefore, our goals were to use dietary intervention to determine whether increased lipid load exacerbates steatosis and hepatic fibrosis in this model and to employ both targeted and untargeted metabolomics to further understand the metabolic consequences of GNMT deletion." (PMID 32951289, 2020). "For example, a study showed that metformin combined with 1,2,3,4,6-penta-O-galloyl-β-d-glucopyranoside (PGG), an inducer of glycine N-methyltransferase (GNMT) expression, which is the most downregulated protein in steatosis liver, reversed all biochemical and histopathological features of MASLD." (PMID 39409124, 2024). "Moreover, GNMT −/− mice developed fatty liver, fibrosis, and HCC, demonstrating that the regulation of SAM levels in the liver is important to prevent steatosis and progression to HCC." (PMID 36144184, 2022). "GNMT‐/‐ mice did appear to have microvesicular steatosis in the liver when compared to WT mice but this was not quantified." (PMID 32951289, 2020).
Hepatic steatosis (12 papers, 2016 to 2026). Steatosis is a term used to denote lipid accumulation within hepatocytes. "Other studies have shown that GNMT is also strongly correlated with the pathogenesis of metabolic dysfunction-associated fatty liver disease (MAFLD)." (PMID 41828318, 2026). "Moreover, loss of liver glycine N-methyltransferase (GNMT) induces hepatic steatosis and disease progression in HCC." (PMID 39273339, 2024). "The downregulation of the gene glycine N-methyltransferase (GNMT), mimics the loss of GNMT in liver oxidative metabolism which promotes liver steatosis." (PMID 38365720, 2024). "Studies have shown that the deletion of the GNMT (glycine N-methyltransferase) gene leads to the development of a fatty liver and fibrosis in mice." (PMID 36139459, 2022). "As a consequence, GNMT mice−/− are characterized by reduced gluconeogenesis due to a decrease in precursors, and hepatic steatosis due to enhanced citrate availability." (PMID 31208147, 2019). "By contrast, decreased GNMT expression is observed in NAFLDs, both in animal models receiving a high-fat diet and in patients with hepatic steatosis." (PMID 31208147, 2019). "Importantly, GNMT expression is decreased both in the liver of animal models receiving a high-fat diet and in patients with hepatic steatosis." (PMID 31208147, 2019). "We now demonstrate that hepatic steatosis and fibrosis in GNMT‐/‐ mice are not exacerbated after long‐term consumption of high‐fat diet (HFD) and that GNMT‐/‐ mice are resistant to HFD‐induced weight gain suggesting that lipotoxicity is not a major contributor to liver damage in this model." (PMID 32951289, 2020). "Although it is not clear that PEMT dependent triglyceride (TG) synthesis contributes significantly to hepatic steatosis nor whether lipotoxicity is a significant contributing factor to liver damage in GNMT‐/‐ mouse liver (Silva, Kelly, Al Rajabi, & Jacobs, 2014)." (PMID 32951289, 2020).
liver disease (11 papers, 2018 to 2026). "Glycine N-methyltransferase (GNMT) is the most important enzyme regulating S-adenosyl-L-methionine metabolism that is frequently decreased in liver disease, including NAFLD, cirrhosis, and HCC." (PMID 34572442, 2021). "Platelets are sequestered in the spleen of subjects with liver disease and we observed significant splenomegaly in GNMT‐/‐ mice." (PMID 32951289, 2020). "In the present study, we demonstrated for the first time the in vivo correction of diverse liver disease models by gene therapy using a recombinant AAV8 vector containing human GNMT cDNA." (PMID 30217986, 2018). "The amount of GNMT was reduced from the early to late stage of liver disease by 6.6 fold and by 9 fold in the mono- and co-infected patients, respectively." (PMID 30138348, 2018). "Finally, a significant correlation between reduced expression of hepatic GNMT and increased levels of miR-873-5p in the serum of a cohort of patients with early and advance cholestatic liver disease was detected in 19 paired samples." (PMID 30237481, 2018). "Ammonia homeostasis is altered during liver diseases and, during DILI, it is accompanied by decreased glycine N-methyltransferase (GNMT) expression and S-adenosylmethionine (AdoMet) levels that suggest a reduced methionine cycle." (PMID 35624761, 2022). "Data highlighting that attenuation of GNMT was found at early stages of liver disease, where fibrosis is still not prominent, points to GNMT deficiency as a contributor/mediator of fibrogenesis rather than a consequence." (PMID 30237481, 2018). "To elaborate, transcription of the GNMT gene was augmented by approximately 15 fold in Huh7.5.1 (dotted bar), but was reduced in the presence of regulatory proteins of HCV (APC140), mimicking reduction of the gene expression at different stages of liver diseases by mono- and co-infection." (PMID 30138348, 2018).